BRAF (B-Raf proto-oncogene, serine/threonine kinase)
Diseases named in the same sentence as BRAF in open-access papers (continued):
Sharing a sentence is not in itself a finding about the gene and the disease.
tumor (continued). "The biological behavior of a BRAF-mutant tumor is profoundly influenced by its tissue of origin, co-occurring mutations, and microenvironmental context." (PMID 40332392, 2025). "Clonality, spread with tumor dedifferentiation or metastatic PTC cells, and coexistence with TERTp, BRAF, RAS, and PIK3CA mutations were also investigated." (PMID 40272676, 2025). "NCCN and ESMO recommend, at minimum, testing for fusions in FGFR2 and NTRK, mutations in IDH1 and BRAF, over-expression or amplifications of HER2/ERBB2, tumor-mutational burden (TMB), and microsatellite instability (MSI)." (PMID 39996880, 2025). "An assessment of the impact on survival of BRAF V600E mutational status in the context of CDKN2A deletions and tumor location was performed." (PMID 40860828, 2025). "In both cohorts, lower CDX2 and SATB2 expression levels were associated with proximal tumor location, high tumor grade, MMR deficiency, and BRAF V600E mutation (p < 0.001 for all)." (PMID 39998677, 2025). "Together, these findings identify the SPACA6-hosted miR-99b~125a~let-7e cluster as a regulator of BRAF/MEK inhibitor resistance through promotion of tumor survival and of an immunosuppressive microenvironment." (PMID 41550951, 2025). "In subgroup analysis, the patients with left colon localization, BRAF wild type tumor, and maintenance treatment had significantly better PFS (p: 0.045, p: 0.037, p: 0.007, respectively)." (PMID 41294701, 2025). "The approach varied, but typically, if a tumor showed MLH1/PMS2 deficiency and either BRAF positivity or hypermethylation, it was considered likely sporadic, and germline testing was discouraged or pursued only if clinical suspicion remained high." (PMID 40426889, 2025). "Tumour‐infiltrating lymphocytes were an independent predictor of PFS in BRAF+MISSONI (p = 0.016, HR = 0.36, CI = 0.153–0.83)." (PMID 39788558, 2025). "Next-generation sequencing (NGS) has been proposed as a comprehensive tool for genomic profiling, enabling the simultaneous detection of multiple gene mutations, including BRAF, as well as an assessment of MSI status and tumor mutational burden (TMB)." (PMID 40647370, 2025). "In both cohorts, mucinous differentiation was associated with proximal tumour location, high tumour grade, MMR deficiency and BRAF mutation." (PMID 39966658, 2025). "AM tumors are also often BRAF wild-type and have low tumor infiltration, making treatment with existing BRAF/MEK inhibitors and immunotherapies particularly challenging." (PMID 39858514, 2025). "This multi-targeted approach allows sorafenib to inhibit both MAPK signaling driven by mutant BRAF and angiogenic pathways critical for tumor growth, offering a mechanistic rationale for its efficacy in BRAF non-V600E-mutant NSCLC." (PMID 40332392, 2025). "One key route involves activation of bypass pathways such as PI3K/AKT/mTOR, allowing tumor cells to maintain growth despite BRAF inhibition." (PMID 41008893, 2025). "Meanwhile, BRAF (B-Raf Proto-Oncogene, Serine/Threonine Kinase) gene mutation, principally the V600E variant, is detected in 8–15% of CRC patients and is correlated with more aggressive tumor progression and poorer survival outcomes." (PMID 40949797, 2025). "BRAF alterations are currently detected through analysis of tumor tissue obtained during tumor resection." (PMID 39751690, 2025). "Emerging evidence suggests that genetic alterations leading to MAPK/ERK pathway dysregulation (e.g., RAS, BRAF) facilitate complex interactions between tumor cells, the tumor microenvironment, and the immune system." (PMID 40666093, 2025). "In studies evaluating resistance in patients with BRAF mutations, the primary resistance rates were observed to be 36% in mutant-BRAF tumours and 33% in wild-type-BRAF tumours when PD-1 inhibitors were used as the first-line therapy." (PMID 41010951, 2025).
tumor (continued). "BRAF V600E mutation is the most common mutation in PTC and has a significant impact on tumor invasiveness, the effectiveness of radioactive iodine therapy, and long-term prognosis." (PMID 40900897, 2025). "BRAF mutations lead to the constitutive activation of the MAPK/ERK signaling pathway, thereby contributing to tumor growth and metastasis of melanocytes." (PMID 41315179, 2025). "BRAF mutations are common in PTC and have been identified as a key driver that also correlates with aggressive tumor behavior; however, they cannot predict outcomes alone." (PMID 40429790, 2025). "MiR-143, known to target BRAF, has been shown to suppress tumor proliferation and chemoresistance in lung cancer models, suggesting similar potential in SOC." (PMID 41294900, 2025). "Genomic profiling of baseline tumor tissue and ctDNA showed that BRAF-V600E was detected by WES and ctDNA in 476 of 503 (94.6%) and 492 of 544 patients (90.4%) analyzed, respectively." (PMID 39313594, 2024). "We additionally examined the associations between gene markers (fadA, bft, pks, and bai) and tumor stage, location, as well as MMR, BRAF, and HER2 mutation status." (PMID 38649355, 2024). "These patients exhibit features such as BRAF mutations, TGFβ2 mutations, MSI‐H, right‐sided CRC, poor tumor differentiation, and recurrent peritoneal seeding." (PMID 37942534, 2024). "Recent investigations on BRAF inhibitors have shifted to concurrent blockade of ancillary signaling pathways or promoting anti-tumor immune activity." (PMID 38275291, 2024). "Recently, the oncogenic function of TBX3 draws attention, where TBX3 is often up-regulated in tumorigenesis and promotes tumor cell proliferation and metastasis, especially during BRAF/MAPK induced tumorigenesis." (PMID 38750011, 2024). "The detection of BRAF V600E mutations in PXA has emerged as a key focus for targeted therapy, especially for tumours that recur or cannot be surgically removed." (PMID 39161507, 2024). "Microenvironment and transcriptional plasticity generate subpopulations within the tumor, and the use of BRAF inhibitors (BRAFis) contributes to the rise and selection of resistant clones." (PMID 38790661, 2024). "Despite their lower overall CNV load compared with iCMS2 tumours, several late CNV deletions correlated with shorter survival, while BRAF and RNF43 mutations were early events." (PMID 39112715, 2024). "This is evident in the heterogeneity of tumour responses to PD-1 and BRAF inhibitors, and likely why predictive markers of immunotherapy response and resistance have large variation and limited specificity and performance." (PMID 38241976, 2024). "These variations in resistance highlight the importance of taking tumor histology into account when considering treatment options for BRAF-mutant cancers." (PMID 38539548, 2024). "Multiple Cox regression analysis performed to adjust for prognostic covariates (BRAF genotype and tumour sidedness) disclosed a significant decrease in OS for patients with the p.V600E variant (p = 0.029) but not with loss of CDX2 expression." (PMID 38439814, 2024). "The development of acquired BRAF V600E has been reported to render tumor insensitivity to EGFR-TKIs treatment, indicating potential clinical benefits of EGFR and BARF co-inhibition in cases with dual mutations." (PMID 39135785, 2024). "Another study examined the development of resistance of tumor plasma cells to treatment with BRAF inhibitors." (PMID 39273371, 2024). "She received erlotinib treatment after the detection of coexistent EGFR L858R/G719S and BRAF V600E via next-generation sequencing of resected tumor tissue." (PMID 39135785, 2024). "Hotspot mutations of the oncogenes, BRAF, and RAS lead to constitutive signaling of the MAPK regulatory pathways, enhancing tumor growth and promoting disease progression." (PMID 38254853, 2024).
tumor (continued). "In line, a study using BRAF fusion-driven neural stem cells showed the importance of microglia recruitment for tumor formation in vivo." (PMID 38630384, 2024). "Altogether, 83 FFPE tumor tissues from CRC patients listed in the NCI database were analyzed for microsatellite instability status, presence of BRAF and KRAS/NRAS mutations, and neoplastic cell percentage in tissue samples." (PMID 38539463, 2024). "The results revealed, on tissue, MSI-H, tumor mutational burden (TMB) of 17.65 mutations per megabase (Muts/Mb), and a BRAF V600E mutation, while the liquid biopsy confirmed the MSI-H, TMB-H (27 Muts/Mb), and the BRAF V600E mutation, among others." (PMID 38957326, 2024). "Conversely, KRAS (p = 2.67e−90), FBXW7 (p = 1.29e−14), BRAF (p = 9.32e−8), GNAS (p = 2.54e−29), and SMAD2 (p = 3.93e−5) mutated tumors were significantly more common in MSLN high expressing tumor samples versus MSLN low expressing tumor samples." (PMID 39174744, 2024). "All multiplexed ddPCR assays in our study demonstrated BRAF exon 15 duplications on tumor gDNA samples." (PMID 38371226, 2024). "It has been suggested that TEADs are mediators of the EGFR/RAS/RAF/MAPK pathway and play a crucial role in tumor progression and drug resistance in NSCLC with EGFR, KRAS, or BRAF mutation." (PMID 38499647, 2024). "This mutation induces the constitutive activation of BRAF and downstream MAPK signaling and subsequently promotes excessive proliferation and survival of tumor cells." (PMID 38839106, 2024). "V600E mutant BRAF activates downstream signal transduction in a constitutive fashion and thereby facilitates the initiation and progression of tumor cells in a variety of human cancers." (PMID 38791574, 2024). "Tumors with BRAF high-level amplification and gain had significantly higher median tumor sizes compared to those with neutral copy numbers (p = 0.019 and p = 0.013, respectively)." (PMID 38919805, 2024). "Targeted therapy with BRAF inhibitors results in a fast and direct therapy response with rare primary resistance, which is essential in the treatment of patients with rapid tumor progress, high tumor burden, or cerebral metastases." (PMID 39125519, 2024). "MEK inhibitors, particularly when combined with BRAF inhibitors, have been found to effectively suppress tumor development and improve outcomes in some malignancies." (PMID 38501105, 2024). "The concordance of CRC mutations in both tumor tissue and plasma cfDNA was also studied, which underlined the concordance of 96% KRAS and 100% BRAF mutations." (PMID 38770216, 2024). "In one of the largest tumor-agnostic studies, BRAF/MEK inhibition with D/T was shown to have a median PFS of 11.4 months, ORR of 38%, and median duration of response of 25.1 months." (PMID 38814411, 2024). "assessed 55 tumor lesions from 18 cases of multifocal PTC for genome-wide allelic imbalances (AI) and BRAF V600E mutation status." (PMID 39135992, 2024). "LY3009120 or combinations with CDK4/6-inhibitors such as abemaciclib have shown stronger anti-tumor effects with BRAF-mutant cancer cells than cancer cell lines with various NRAS genotypes." (PMID 38397192, 2024). "Patient MEL30 was diagnosed with a metastatic cutaneous melanoma wild-type (WT) for BRAF and NRAS genes in its primary tumor but a BRAF V600E mutation was present in a resected lymph node metastasis." (PMID 38898234, 2024). "The same primary tumor location suggests that the FBC model truthfully recapitulates human BRAF-mutant serrated CRCs, at least by location." (PMID 36778401, 2024). "KRAS, NRAS and BRAF testing on tissue was performed with real-time PCR and revealed a wild-type tumor." (PMID 39064004, 2024). "A recent study found AIM2 inhibits BRAF mutated CRC growth via caspase-1 in vitro and in vivo, confirming AIM2 overexpression significantly inhibits BRAF-mutated CRC tumor growth and metastasis." (PMID 38455052, 2024).
tumor (continued). "The BRAF gene is responsible for encoding a protein kinase (MAPK) crucial for regulating cellular growth and proliferation within tumor cells." (PMID 38891988, 2024). "Collectively, BRAF/MAPK/c‐Jun induces high miR‐31 expression in PTC to promote tumour progression, metastasis and RAI refractoriness via maintaining Wnt/β‐catenin signalling and dedifferentiating." (PMID 38797942, 2024). "Overall, our single CTC data revealed high genomic intra- and inter-patient genomic diversity in MAPK, MAPK-related and MAPK-independent pathways at resistance to BRAF inhibition, which was missed by bulk analyses on tumour biopsies and cfDNA." (PMID 38177660, 2024). "Only the primary tumour resection at baseline was associated with longer DFS in the overall population and BRAF mutation, and pN+ stage predicted shorter DFS among patients with resected primary tumour." (PMID 38631269, 2024). "The authors also found that tumours of BRAF V600E mice were enriched with Th1 immune signatures, including increased IFN-γ and IFN-α gene sets and increased myeloid-cell enrichment compared to controls." (PMID 39340753, 2024). "PERSEIDA was an observational, prospective study assessing cfDNA RAS, BRAF and EGFR mutations (using IdyllaTM) in first-line mCRC, RAS wild-type (baseline tumor-tissue biopsy) patients (cohort 2)." (PMID 38642257, 2024). "Promising high tumor response rates were achieved using BRAF/MEK inhibitors, however data on their use in low-middle-income-countries (LMICs) are limited." (PMID 39399174, 2024). "NGS also allows to identify BRAF V600E mutations and TMB-H tumors as well as other rare molecular alterations (such as NTRK fusions) that have FDA approved tumor-agnostic treatment options." (PMID 39361075, 2024). "Its expression correlates with BRAF and KRAS mutations, poor differentiation, and advanced tumour stages, marking it as a significant prognostic marker." (PMID 39456841, 2024). "BRAF mutation in NSCLC is often associated with increased programmed death ligand 1 (PD-L1) expression and tumor mutational burden (TMB)." (PMID 39337530, 2024). "Here, we show that meningeal cell-induced SERPINA3 expression at the tumor/stroma interface promotes the amplification of PI3K/AKT signaling and the reactivation of ERK in the tumor cells, thereby overcoming BRAF/MEK inhibition." (PMID 38866016, 2024). "Although rare, this can coincide with dedifferentiation of tumor histology as seen with rare cases of anaplastic transformation after BRAF inhibitor therapy." (PMID 38275291, 2024). "Treatment with BRAF/MEK inhibitors has been shown to induce a favorable tumor immune microenvironment in melanoma." (PMID 38907159, 2024). "Animal studies have confirmed that combinations of BRAF inhibitors and checkpoint inhibitor immunotherapies synergistically reduce tumor volume in mouse models of carcinoma." (PMID 39290709, 2024). "Patient response to EGFR inhibitors is influenced by factors such as tumour sidedness and RAS/BRAF mutational status." (PMID 38414064, 2024). "Even though limited by sample size, BRAF mutation was found to increase infiltration of cytotoxic T cells in both MSI and MSS tumours to similar levels." (PMID 38040818, 2024). "It has also been shown that co-targeting COX2 with BRAF + EGFR durably inhibits tumor growth capacity in patient-derived tumor xenograft models." (PMID 38717677, 2024).
tumor (continued). "MEK inhibitors (MAPKi), such as cobimetinib or trametinib, and immune checkpoint inhibitors such as atezolizumab are used in clinic in combination with BRAF inhibitors to delay the onset of drug-resistant tumor outgrowth." (PMID 38965534, 2024). "In contrast, ETBF colonization in BLM mice resulted in an additional new tumor locus in the mid-proximal part of the colon, which resembles the right-sided location of BRAF mutant tumors observed in CRC patients." (PMID 38893159, 2024). "Droplet digital PCR (ddPCR) using a commercial BRAF V600 screening kit revealed that CSF was clearly positive for circulating tumor DNA (ctDNA) with 45 mutant and 284 wt copies, corresponding to a variant allele frequency of 13.6%." (PMID 38388693, 2024). "Clinical studies have shown that combining B-Rapidly Accelerated Fibrosarcoma (B-raf proto-oncogene or BRAF) and tyrosine kinase (TK) inhibitors effectively stops tumor growth and overcomes resistance." (PMID 39640522, 2024). "We believe that Group 1 BRAF V600E-mutant tumor represents a previously unrecognized cluster with a strong association between neuroimaging features and genotype in LEAT, irrespective of histopathological and integrated diagnoses." (PMID 39081340, 2024). "Consistent with an increase in MAPK- and PI3K-related signaling observed at the tumor-meningeal stroma interface, we also observed the conditioned CSF to promote recovery of pERK (p < 0.05) and amplify pAKT (p < 0.05) following BRAF inhibitor treatment." (PMID 38866016, 2024). "The human patient case study revealed a population of MET-amplified tumor cells that were resistant to EGFR-/BRAF-targeted therapy." (PMID 39626159, 2024). "About half of the tumours were RAS mutated (53%), with a very small percentage of BRAF mutated (2%) and almost all were proficient mismatch repair/microsatellite stable (pMMR/MSS) (98%)." (PMID 38631269, 2024). "The only BRAF ctDNA-positive patient at the postoperative surveillance had incomplete tumor resection and suspicion of persistent disease." (PMID 39336882, 2024). "While the more linear impact on growth from increasing Cobimetinib doses on the BRAF mutant tumor subjected to a constant Belvarafenib dose indicates that the drugs are acting in a more additive fashion." (PMID 39199684, 2024). "This small subgroup of patients had comparable outcomes following CRS to wild‐type patients, therefore within the limitations of our study, we believe BRAF mutant tumours should still be considered for CRS." (PMID 39011877, 2024). "BRAF mutations can lead to the secretion of various cytokines and chemokines (such as CCL2, CCL5, and CXCL8) by tumor cells, altering the surrounding tumor microenvironment." (PMID 39529955, 2024). "In this international, multicenter, single-arm phase 2 trial, tovorafenib monotherapy resulted in clinically meaningful, rapid and durable tumor responses in children and young adults with BRAF-altered relapsed/refractory pLGG." (PMID 37978284, 2024). "The functional relevance of these pathways is supported by increased expression in alternative pathways such as PI3K-AKT and mTOR after tumor dedifferentiation and BRAF inhibitor treatment." (PMID 38275291, 2024). "We find that BRAF V600E tumors lack significant synergy (low Bliss excess) but still achieve consistently strong tumor suppression (high GR values) from drug regimens with as low dosing as Belvarafenib 100 mg QD and Cobimetinib 20 mg QD." (PMID 39199684, 2024). "Molecular testing of her tumor shows microsatellite stable disease, wild-type RAS, and a BRAF V600E mutation." (PMID 38888919, 2024). "Sistrunk surgery with additional ipsilateral thyroidectomy was performed if the patient was ≥ 45 years old, had a tumor ≥ 4 cm, or was BRAF gene positive." (PMID 38941410, 2024). "While BRAF inhibitors initially induce tumor regression, disease recurrence eventually develops due to acquired tumor resistance." (PMID 38945960, 2024).